CDKN2A (cyclin dependent kinase inhibitor 2A)
Diseases named in the same sentence as CDKN2A in open-access papers (continued):
Sharing a sentence is not in itself a finding about the gene and the disease.
tumor (continued). "Conversely, lack of CDKN2A/B inactivation (either heterozygous or homozygous) in a tumor that otherwise histologically meets the diagnostic criteria for ANNUBP would not alter the diagnosis." (PMID 39500722, 2025). "CDKN2A gene codes for cell cycle inhibitors, p16 signalling and SMAD4, which act as transducers of the transforming growth factor beta (TGF-β) signalling pathway, and are two commonly mutated tumor suppressors found in about 20% of PDAC cases." (PMID 40230862, 2025). "Elevated protein levels of CDKN2A were observed in both cancerous tissues and tumor cell lines." (PMID 39895793, 2025). "Similarly, miR-146a has been identified as another tumor-suppressive miRNA that inhibits breast cancer cell proliferation by directly targeting the well-known cell cycle regulator CDKN2A." (PMID 41011238, 2025). "Notably, several genes involved in cell cycle regulation (CCND2, CDKN2A/C), tumor microenvironment (COL3A1, COL1A1), and growth factor signaling (FGF18, ERBB2) showed significant upregulation with fold changes ranging from 1.5 to 2.0." (PMID 41419500, 2025). "Furthermore, YM201636 and VE-822, both high-affinity drugs that bind to CDKN2A, exhibited promising anti-tumor effects in vivo." (PMID 41341386, 2025). "We did not identify Cdkn2a loss in 2 of the 13 analyzed tumors, thus being probably not mandatory for tumor progression." (PMID 41223283, 2025). "The review highlights the dual role of DNA methylation in BC: global hypomethylation can activate transposable elements and oncogenes, whereas focal hypermethylation silences tumor-suppressor genes like CDKN2A, especially detrimental in older tissues that rely on these genes for senescence control." (PMID 40918525, 2025). "Moreover, CDKN2A promotes cuproptosis resistance by modulating glycolysis and copper homeostasis, thereby contributing to a malignant phenotype and a pro-tumor microenvironment." (PMID 40406488, 2025). "Similarly, the concurrent loss of CDKN2A and CDKN2B, which encode critical cell cycle regulators, contributes to uncontrolled cell division and tumor progression." (PMID 40223032, 2025). "Nearly all tumors with CDKN2A/B homozygous or heterozygous loss (91.7%) clustered together, irrespective of tumor grade (cluster 1)." (PMID 39584448, 2025). "CDKN2A alterations, predominantly occurring in the invasive component, may act as drivers of tumor invasion and serve as potential biomarkers for identifying high‐risk cysts." (PMID 40371932, 2025). "Interestingly, our analysis also revealed two cases showing a completely preserved MTAP expression (100% of positive tumour cells), even though with a significant rate (>20%) of CDKN2A homozygous deletion by FISH." (PMID 40566743, 2025). "Moreover, the average expression level (rating score) of CDKN2A were elevated in LUAD tissues compared to those in adjacent non-tumor tissues." (PMID 41341386, 2025). "Knockdown of COX6A1 significantly upregulated senescence-associated genes, such as CDKN1A and CDKN2A, indicating that COX6A1 may inhibit tumor progression by inducing senescence." (PMID 40331946, 2025).
tumor (continued). "Additionally, this stratification revealed significant disparities in gender distribution, primary tumour sites, and histologic grades between groups, emphasizing the intricate relationship between CDKN2A expression and clinical outcomes." (PMID 38751024, 2024). "Changes in the protein levels in HNSCC subtypes may reflect the diversity of molecular pathways of tumor development depending on the subtype or may also be responsible for the involvement of CDKN2A and Ki-67 in the carcinogenesis process." (PMID 39590385, 2024). "Our results showed that changes in protein levels in HNSCC subtypes may reflect different molecular pathways of tumor development or may also be responsible for the involvement of CDKN2A and Ki-67 in the carcinogenesis process." (PMID 39590385, 2024). "The results show that MEF2D is enriched in CDKN2A-expressing tumor epithelia and can target CDKN2A." (PMID 38888512, 2024). "Mice lacking two Ink4 genes, such as Cdkn2a/Cdkn2b or Cdkn2a/Cdkn2d, display increased tumor susceptibility compared to p16INK4a-null mice." (PMID 38561743, 2024). "Tumor epithelium displayed a higher density of CDKN2A positivity in comparison with normal tissue." (PMID 38888512, 2024). "In this study, we examined the prevalence of CDKN2A MUT and DEL in 25,755 tumor samples from 33 cancer types in the MSK-MetTropism cohort and discovered associations between CDKN2A MUT or DEL and clinical outcomes in pan-cancer patients with/without ICIs treatment." (PMID 38822443, 2024). "Unlike the gain of methylation at the Cdkn2a/2b gene cluster, the decrease in DNA methylation of genes involved in tumor suppression was associated with an increase in chromatin accessibility." (PMID 38867059, 2024). "However, a recent study reported RB1 deletions (possibly mostly monoallelic) in 26% of 118 MPM samples including in one‐third of tumours with CDKN2A deletions." (PMID 36453028, 2024). "Furthermore, the specific genomic alterations, such as CDKN2A and APC mutations, associated with the formation of C0 and C1 subpopulations provide insight into the potential drivers of tumour cell heterogeneity." (PMID 38279519, 2024). "Conversely, in TCGA dataset, we assessed the extent of immune cell infiltration using CIBERSOFT and observed that CDKN2A-MUT, CDKN2A-ALT, or CDKN2A-DEL cases displayed reduced immune cell infiltration and lower expression levels of crucial genes associated with tumor immune function." (PMID 38822443, 2024). "Genomic studies have revealed mutations in genes such as SETD2, CDKN2A, SMARCB1, and NF2, which may contribute to the tumor's aggressive phenotype." (PMID 39310439, 2024). "Furthermore, the CDKN2A gene, a cyclin-dependent kinase 2A inhibitor capable of regulating the cell cycle and exhibiting tumour suppressor activity, was found to be downregulated in HSCs from patients with AML." (PMID 38969699, 2024). "The recurrent tumor acquired CCND3 amplification on a subsequent resection, followed by the acquisition of CDKN2A/B loss, mismatch repair deficiency, and alkylator-induced somatic hypermutation, which was identified in a liver metastasis that had a Ki67 of 50%." (PMID 38758238, 2024). "The up-regulation of CDKN2A in CRC tissue and the interaction with the KRAS mutation status (meaning more up-regulation in the presence of mutation) remained significant even when the tumor stage was taken into account." (PMID 39125664, 2024). "An abnormal modification in CDKN2A could result in the silencing of the CDKN2A gene, impacting its tumour-suppressive functions." (PMID 38255946, 2024).
tumor (continued). "Additionally, stratified survival analysis suggested that CDKN2A-ALT patients were shorter OS than CDKN2A-WT patients across multiple levels of CNA, MSI, TMB, age, mutation count, gender, tumor purity and race." (PMID 38822443, 2024). "However, false-negative results were identified (three patients with CDKN2A heterozygous deletion, with a total score below 9) and one false-positive case (a CDKN2A-wild type tumor, detected by FISH as monosomy, with scoring values above 9)." (PMID 38667459, 2024). "How CDKN2A regulates cuproptosis and tumor progression is still awaiting further in-depth research." (PMID 38888512, 2024). "In assays of immune cell infiltration, high CDKN2A expression in tumor tissue was obviously positively related to increased numbers of activated immune cells, which suggested that CDKN2A may play a key role in tumor immunity." (PMID 39744627, 2024). "Moreover, we found an association between CDKN2A and Ki-67 concentrations and the HPV status in tumor and margin samples." (PMID 39590385, 2024). "Moreover, the tumor suppressors ARID1B, CDKN2A and NF1 were commonly affected by chromosomal copy loss." (PMID 38191367, 2024). "In patient TFCP2-HD-4, the intragenic ALK deletion and homozygous CDKN2A loss were not detectable in the early tumor but in the local recurrence 28 months later." (PMID 38168093, 2024). "Additionally, ATRX mutations, EGFR (epidermal growth factor receptor) alterations, CD70, CD147, CDKN2A deletions, exosomes, cfDNA (cell-free DNA), ctDNA (circulating tumor DNA), and CTCs (circulating tumor cells) stand out as significant markers." (PMID 38732975, 2024). "Deletion of CDKN2A was detected in paired tumor foci of P1336." (PMID 38956687, 2024). "Methylation of CDKN2A/p16INK4A was identified in 13 tumor samples and 12 non-tumor tissue samples." (PMID 38716944, 2024). "Next, it is noteworthy to mention the presence of CDKN2A deletion in our patient's tumor." (PMID 39108689, 2024). "Furthermore, CDKN2A is one of the most extensively studied tumour suppressor genes and plays a critical role in cell cycle progression, cellular senescence, and apoptosis." (PMID 38969699, 2024). "Conversely, CDKN2A upregulation induces cell cycle arrest and inhibits tumor growth." (PMID 38438773, 2024). "MMP7 and SPP1 levels were also higher in both CDKN2A+ tumor regions and nearby CDKN2A+ regions." (PMID 38888512, 2024). "Similarly, the CDKN2A (p16/INK4a) gene, which inhibits cell cycle progression, is often hypermethylated, thereby promoting tumor growth." (PMID 39596558, 2024). "NK cells activated, monocytes, Tregs, B cells naive, T cells CD8, T cells CD4 memory resting, and macrophages M2 were lower in CDKN2A-MUT or DEL patients’ tumor tissue than in CDKN2A-WT patients, implying an immune cold tumor immune microenvironment in TCGA pan-cancer with CDKN2A VAR." (PMID 38822443, 2024). "Historically, research has primarily centered on CDKN2A’s role as a tumor suppressor." (PMID 38918694, 2024). "A next-generation sequencing transcriptomic immune profile analysis applied to 28 persistent CIN3 lesions and 14 normal biopsies identified four genes, the immune markers ARG1 and HLA-DQB2 and the tumour markers CDKN2A and KRT7, as possible markers for differentiating between CIN3 and normal tissue." (PMID 39712018, 2024). "A significant upregulation of CDKN2A was observed in the primary tumour tissues (p=<10-12)." (PMID 38164368, 2024). "We also found that NPC268 consistently harbors CN losses in three chromosomal arms in both tumor and cell line, including the 9p21.3 co-deletion of CDKN2A and MTAP which is a common event in NPC, implying that NPC268 could be vulnerable to MAT2A inhibitors." (PMID 38358347, 2024).
tumor (continued). "Group 2 Schwann cell tumors comprise a transitory state with loss of tumor suppressors such as CDKN2A/B potentially consistent with ANNUBPs that have not yet fully progressed to a malignant, de-differentiated state." (PMID 38216572, 2024). "Notably, CDKN2A ALT frequency was positively related to tumor-specific objective response rates to ICIs in MSK MetTropism and OrigiMed 2020." (PMID 38822443, 2024). "Within the tumor area, we designated spots as CDKN2A+ and CDKN2A-." (PMID 38888512, 2024). "Patients with HOMDEL of CDKN2A exhibited lower levels of deep white matter invasion (47.1%), defined as “Enhancing or nCET tumor extending into the internal capsule, corpus callosum or brainstem” compared to those with HETLOSS or no alteration (75%) (p = 0.041)." (PMID 38135704, 2023). "The coincidence between CSF and tumor tissue for CDKN2A/B deletion was 87.5%." (PMID 37822669, 2023). "To verify whether four EMT-related genes (SIX1, SIRT2, CDKN2A and PGR) are associated with tumor metastasis, we performed transwell migration assays, transwell invasion assays and wound healing assays to investigate their relationship." (PMID 37723477, 2023). "It is a highly complex genomic region that includes the tumour-suppressor genes CDKN2A and CDKN2B." (PMID 37761946, 2023). "Inactivating mutations and deletions of 3 tumour suppressor loci, namely CDKN2A/B, NF2, and BAP1 predominate, with functional loss of each tumour suppressor occurring in over 50% of cases and single or combinatorial loss of the 3 loci found in all possible permutations." (PMID 37441092, 2023). "In conclusion, combined p16 and MTAP immunohistochemistry is a cost-effective surrogate for CDKN2A-MTAP genetic alterations that can be reliably used to detect homozygous deletions and visualize the spatial heterogeneity of the CDKN2A-MTAP gene complex within the same tumor sample." (PMID 37894345, 2023). "Notably, both CDKN1A and CDKN2A belong to the same family (cyclin dependent kinase inhibitor) and show the same change trend in the tumor development stage while with different trends in the development stage." (PMID 38070141, 2023). "Moreover, it was proven that the presence of mutation, differential expression, or copy number variation in the CDKN2A gene enhances tumor formation." (PMID 37415453, 2023). "Collectively, the infiltration and the exhaustion status of the CD8 T cell are important factors that control tumor growth, therefore the current study asked about the consequences of CDKN2A alterations under tumor conditions on the infiltration and the status of the CD8 T cell." (PMID 37626750, 2023).
tumor (continued). "In the initial discovery cohort, they found 38 CDKN2A/B HD tumours." (PMID 37504251, 2023). "The study offered RNA analysis for CDK4 and CDKN2A in the archival tumor material with the assumption that if a biomarker expression fitting with the inclusion criteria was found, then the screening at baseline would render a highly probable similar RNA expression." (PMID 37875500, 2023). "Interestingly, CDKN2A, a well-known tumour suppressor gene, is highly expressed in pan-cancer types." (PMID 36895378, 2023). "After confirming the significant upregulation of CDKN2A in most of the analyzed tumors, we asked if that upregulation could affect tumor progression." (PMID 37626750, 2023). "Although the mutation predominates in low-grade CNS tumors, when combined with other mutations, most commonly CDKN2A deletion, BRAFV600E-mutated CNS tumors are prone to develop high-grade features, and therefore BRAFV600E-mutated CNS are a paradigm for tumor progression." (PMID 37920169, 2023). "Tumor cells showed amplification of MDM2 gene and a homozygous loss of CDKN2A on 9p21." (PMID 37818167, 2023). "We found that five cuprotosis molecules, DLAT, PDHA1, FDX1, GLS and CDKN2A, were significantly different between paired tumour and adjacent non-tumour samples from the TCGA-STAD cohort, and LIAS, DLD, DLAT and MTF1 were significantly different among the four pathologic T categories 1–4." (PMID 36895378, 2023). "The study also aimed to identify the DNA methylation status of CDKN2A, as an important form of epigenetic regulation, investigate the shapes of CDKN2A genetic alterations, and study the outcome of these alterations on the human immune cells and cytokines that play major roles in tumor progression." (PMID 37626750, 2023). "We used the pan-cancerous immunocyte infiltration data from the TIMER2 database for Spearman correlation analysis to mine the correlations between CDKN2A expression and immunocyte infiltrations to further analyze the relationship between CDKN2A expression and tumor immunity." (PMID 36961395, 2023). "The effects of CDKN2A/B deletion on tumour development may also be mediated, at least in part, by co-deletion of adjacent genes in the 9p21 region, such as MTAP, IFNA1, IFNB1, and ANRIL." (PMID 37504251, 2023). "Additionally, the last few years had witnessed several advancements in the field of tumor immunotherapy; therefore, it was important to investigate the correlation between CDKN2A alterations and the levels of several immune components." (PMID 37626750, 2023). "The investigators have discovered that the suppresion of CDKN2A expression could inhibit tumor cell proliferation and diminish the epithelial-mesenchymal transition (EMT) progression in CRC." (PMID 37974218, 2023). "Our results could provide some clues for further research on the potential role of CDKN2A in tumor immunotherapy to explore and practical application." (PMID 36961395, 2023). "The CNA profiles were similar between the NF1-associated and sporadic tumours, although there was a trend towards a higher burden of CNAs (P = 0.07), LOH (P = 0.05, both from Wilcoxon's test), and homozygous deletion of CDKN2A (OR = 2.4, P = 0.06 from Fisher's exact test) in NF1-associated tumours." (PMID 37837931, 2023). "One tumor harbored a CDKN2A homozygous deletion and one tumor had an oncogenic BRCA2 alteration." (PMID 38143440, 2023). "CDKN2A heterozygous deletions (>30%) in tumor cells were detected in only one case." (PMID 38239634, 2023). "The prognostic role of CDKN2A in cancers reflects the tumor suppressor function of it in cancers." (PMID 36961395, 2023). "CDKN2A, located on chromosome 9p21.3, regulates cell division and prevents tumor formation." (PMID 37928523, 2023).